SLC25A31 (solute carrier family 25 member 31)
Description:
ADP:ATP antiporter that mediates import of ADP into the mitochondrial matrix for ATP synthesis, and export of ATP out to fuel the cell (By similarity). Cycles between the cytoplasmic-open state (c-state) and the matrix-open state (m-state): operates by the alternating access mechanism with a single substrate-binding site intermittently exposed to either the cytosolic (c-state) or matrix (m-state) side of the inner mitochondrial membrane (By similarity). Specifically required during spermatogenesis, probably to mediate ADP:ATP exchange in spermatocytes. Large ATP supplies from mitochondria may be critical for normal progression of spermatogenesis during early stages of meiotic prophase I, including DNA double-strand break repair and chromosomal synapsis (By similarity). In addition to its ADP:ATP antiporter activity, also involved in mitochondrial uncoupling and mitochondrial permeability transition pore (mPTP) activity (By similarity). Plays a role in mitochondrial uncoupling by acting as a proton transporter: proton transport uncouples the proton flows via the electron transport chain and ATP synthase to reduce the efficiency of ATP production and cause mitochondrial thermogenesis (By similarity). Proton transporter activity is inhibited by ADP:ATP antiporter activity, suggesting that SLC25A31/ANT4 acts as a master regulator of mitochondrial energy output by maintaining a delicate balance between ATP production (ADP:ATP antiporter activity) and thermogenesis (proton transporter activity) (By similarity). Proton transporter activity requires free fatty acids as cofactor, but does not transport it (By similarity). Among nucleotides, may also exchange ADP for dATP and dADP. Also plays a key role in mPTP opening, a non-specific pore that enables free passage of the mitochondrial membranes to solutes of up to 1.5 kDa, and which contributes to cell death (By similarity). It is however unclear if SLC25A31/ANT4 constitutes a pore-forming component of mPTP or regulates it (By similarity).
Synonyms: ANT 4; AAC4; ANT4; DKFZP434N1235; SFEC35kDa
Tractability: Antibody: UniProt predicts a signal peptide or a membrane-spanning region; its Gene Ontology location is reachable by antibodies, with medium confidence. PROTAC: ubiquitination databases record sites on it; its protein half-life has been measured.
Gene: Protein-coding gene on chromosome 4 (127,730,400 to 127,774,292, forward strand). Ensembl gene ENSG00000151475.
Subcellular location: Mitochondrion inner membrane; Membrane; Cell projection, cilium, flagellum membrane
Subcellular location (Human Protein Atlas): Mitochondria
Gene Ontology:
Molecular function: ATP:ADP antiporter activity; protein binding
Biological process: male meiosis I; mitochondrial ATP transmembrane transport; regulation of mitochondrial membrane permeability; spermatogenesis; mitochondrial ADP transmembrane transport; transmembrane transport
Cellular component: membrane; mitochondrial inner membrane; mitochondrion; nucleus; mitochondrial permeability transition pore complex
Genetic constraint (gnomAD): Loss-of-function variants: 32 observed, 30.65 expected, observed/expected ratio (o/e) 1.04, 90% interval 0.79 to 1.4. The upper end of that interval is the gene's LOEUF score, 1.4, which puts it in group 5 of 6, group 1 being the genes least tolerant of losing a copy. Missense variants: 319 observed, 370.4 expected, observed/expected ratio (o/e) 0.86, 90% interval 0.79 to 0.94. Synonymous variants: 132 observed, 141.83 expected, observed/expected ratio (o/e) 0.93, 90% interval 0.81 to 1.08.
Homologues: Orthologues: chimpanzee SLC25A31 (99% identical), macaque SLC25A31 (99% identical), rabbit SLC25A31 (95% identical), guinea pig SLC25A31 (94% identical), pig SLC25A31 (93% identical), dog SLC25A31 (92% identical), mouse Slc25a31 (89% identical), rat Slc25a31 (88% identical), Drosophila melanogaster sesB (69% identical), Drosophila melanogaster Ant2 (65% identical), Caenorhabditis elegans R07E3.4 (40% identical). Paralogues in human: SLC25A4 (69% identical), SLC25A5 (67% identical), SLC25A6 (67% identical), SLC25A13 (26% identical), SLC25A12 (26% identical), SLC25A16 (26% identical), SLC25A29 (26% identical), SLC25A36 (26% identical), SLC25A43 (26% identical), SLC25A27 (24% identical), SLC25A32 (24% identical), SLC25A48 (24% identical), and 37 more.
Diseases named in the same sentence as SLC25A31 in open-access papers:
SLC25A31 is named in the same sentence as 10 diseases in open-access papers, as found by Europe PMC text mining. Sharing a sentence is not in itself a finding about the gene and the disease. The quoted sentences say what the papers report.
ovarian serous cystadenocarcinoma (1 paper, 2022). A malignant serous cystic epithelial neoplasm arising from the ovary. "Besides, the mutation of many SLC25s made high-risk effects on the prognosis of ovarian serous cystadenocarcinoma such as SLC25A8, SLC25A24, SLC25A25, and SLC25A31." (PMID 36254139, 2022).
tumor (2 papers, 2020 to 2024). "SLC25A31 results poorly expressed in the 21 “tumor vs. normal” tissue pairs." (PMID 33396658, 2020).
SLC25A31 also shares sentences with these, for which no sentence is quoted: glioblastoma (2 papers); male infertility (2); Obesity (2); brain tumors (1); cancer (1); cardiomyopathy (1); Hypertension (1); Infertility (1).